CPM (carboxypeptidase M)
Description:
Specifically removes C-terminal basic residues (Arg or Lys) from peptides and proteins. It is believed to play important roles in the control of peptide hormone and growth factor activity at the cell surface, and in the membrane-localized degradation of extracellular proteins.
Tractability: Small molecule: it belongs to a druggable protein family. Antibody: UniProt places it where antibodies can reach, with high confidence; its Gene Ontology location is reachable by antibodies, with high confidence; UniProt predicts a signal peptide or a membrane-spanning region. PROTAC: its protein half-life has been measured; a small molecule that binds it is known.
Target class: Metallo protease; Metallo protease MC clan; Protease; Enzyme; Metallo protease M14B subfamily
Gene: Protein-coding gene on chromosome 12 (68,842,197 to 68,971,570, reverse strand). Ensembl gene ENSG00000135678.
Subcellular location: Cell membrane
Subcellular location (Human Protein Atlas): Vesicles
Pathways (Reactome):
Metabolism of proteins: Post-translational modification: synthesis of GPI-anchored proteins
Gene Ontology:
Molecular function: carboxypeptidase activity; metallocarboxypeptidase activity; zinc ion binding
Biological process: anatomical structure morphogenesis; peptide metabolic process; protein processing; proteolysis
Cellular component: cell surface; extracellular exosome; plasma membrane; extracellular region
Genetic constraint (gnomAD): Loss-of-function variants: 31 observed, 41.16 expected, observed/expected ratio (o/e) 0.75, 90% interval 0.56 to 1.02. The upper end of that interval is the gene's LOEUF score, 1.02, which puts it in group 4 of 6, group 1 being the genes least tolerant of losing a copy. Missense variants: 362 observed, 492.09 expected, observed/expected ratio (o/e) 0.74, 90% interval 0.67 to 0.8. Synonymous variants: 170 observed, 184.46 expected, observed/expected ratio (o/e) 0.92, 90% interval 0.81 to 1.05.
Homologues: Orthologues: chimpanzee CPM (99% identical), macaque CPM (97% identical), guinea pig CPM (88% identical), rat Cpm (86% identical), mouse Cpm (85% identical), dog CPM (84% identical), pig CPM (77% identical), tropical clawed frog cpm (54% identical), zebrafish cpm (51% identical), Drosophila melanogaster CG4678 (44% identical). Paralogues in human: CPD (44% identical), CPN1 (40% identical), CPE (39% identical), CPZ (37% identical), CPXM1 (34% identical), CPXM2 (32% identical), AEBP1 (29% identical).
Diseases named in the same sentence as CPM in open-access papers:
CPM is named in the same sentence as 15 diseases in open-access papers, as found by Europe PMC text mining. Sharing a sentence is not in itself a finding about the gene and the disease. The quoted sentences say what the papers report.
colorectal cancer (2 papers, 2017 to 2021). A primary or metastatic malignant neoplasm that affects the colon or rectum. "Mainly, miR-146a-5p promoted the growth of human osteosarcoma by targeting the ZNRF3/GSK3β/β-catenin pathway and enhanced the migration and invasion of human colorectal cancer cells by targeting the carboxypeptidase M/src-FAK pathway." (PMID 34051870, 2021).
Insulin resistance (2 papers, 2017 to 2021). Increased resistance towards insulin, that is, diminished effectiveness of insulin in reducing blood glucose levels. "Recently, CPM and B1R were found upregulated along with the inducible nitric oxide synthase (iNOS) and interleukin-1β (IL-1β) in aorta, renal cortex and liver in a rat model of insulin resistance induced by high glucose feeding." (PMID 28824433, 2017). "This study addresses the hypothesis that inhibition of kininase 1 (carboxypeptidase M, CPM), the key enzyme involved in the biosynthesis of B1R agonists, could exert the same beneficial effects to B1R antagonism in insulin resistance." (PMID 28824433, 2017). "While the inhibition of carboxypeptidase M in rats reverses insulin resistance, and cross-talk between carboxypeptidase N and Carboxypeptidase B2 is observed during complement activation, the functional relevance of the downregulation of this protein with ALT is unknown." (PMID 34203471, 2021).
liposarcoma (2 papers, 2017 to 2025). A usually painless malignant tumor that arises from adipose tissue. "Key genes in this region, including MDM2, cyclase-associated protein (CPM), and solute carrier family 35 member E3 (SLC35E3), are significantly amplified and play a critical role in the progression of dedifferentiated liposarcoma." (PMID 39974236, 2025). "Of particular interest, CPM (carboxypeptidase M) - located at the edge of the 12q amplicon, outside of what was thought to be the key region defined by CDK4 and MDM2 - was amplified in 39 of 50 well- and de-differentiated liposarcomas." (PMID 27732970, 2017).
benign lipomas (1 paper, 2025). "Additionally, research indicates that carboxypeptidase M (CPM), a protein encoded by the CPM gene, serves as a novel tumor marker and aids in the differentiation of ALT/WDLS from benign lipomas and normal adipose tissue." (PMID 40674962, 2025).
breast carcinoma (1 paper, 2026). "Among these proteins, MET is known to be involved in breast cancer, while little is known about the roles of CPM and CST6." (PMID 41514346, 2026).
endometriosis (1 paper, 2019). The growth of functional endometrial tissue in anatomic sites outside the uterine body. "Protein groups were scored for biomarker potential with carboxypeptidase M (CPM) the highest scoring, displaying increased endometrial expression in endometriosis versus both control groups and in both cycle phases (ES/CS = 1.62, ES/PS = 2.53, EP/CP = 2.45)." (PMID 30992697, 2019).
tumor (7 papers, 2004 to 2025). "CPM is responsible for carboxypeptidase M production which is a cleavage enzyme for growth factor and CPM-silencing tumor cells show reduced tumor growth and invasion." (PMID 33498189, 2021). "This was further substantiated by the expression of CPM on differentiated immune cells such as macrophages, and up- or downregulation of CPM in inflammation, tumor and/or tumor environment." (PMID 22479563, 2012). "Additionally, TIMER analysis indicated that CPM expression is correlated with immune cell infiltration, specifically with B cells, CD4+ T cells, CD8+ T cells, macrophages, neutrophils, and dendritic cells, suggesting a potential role for CPM in the tumor microenvironment and immune response." (PMID 40136513, 2025). "Real-time quantitative PCR results disclosed that MPC1, ZG16, RBM47, CPM and DNASE1L3 were expressed at higher levels in adjacent normal tissues than in tumor tissues, and SMOX expression was higher in tumor tissues than in non-tumor tissues." (PMID 38914961, 2024).
infection (1 paper, 2023). The state of being infected such as from the introduction of a foreign agent such as serum, vaccine, antigenic substance or organism. "It is rational to deduce that the activity of blocking local RNA silencing by the ToCV CPm protein would be indispensable for ToCV primary infection at that point the P22 protein was not translated." (PMID 37056753, 2023).
CPM also shares sentences with these, for which no sentence is quoted: cancer (3 papers); angioedema (1); colon cancer (1); dementia (1); hyperprolactinemia (1); lung carcinoma (1); osteosarcoma (1).